ACTN4P1 (actinin alpha 4 pseudogene 1)
Gene: Processed pseudogene on chromosome 4 (116,598,161 to 116,599,611, forward strand). Ensembl gene ENSG00000213493.
Diseases named in the same sentence as ACTN4P1 in open-access papers:
ACTN4P1 is named in the same sentence as 1 disease in open-access papers, as found by Europe PMC text mining. Sharing a sentence is not in itself a finding about the gene and the disease. The quoted sentences say what the papers report.
progeria (1 paper, 2022). "Some genes that are downregulated during aging are upregulated in progeria patients (KRT8, KRT18, UCP2, ADAMTS15, ACTN4P1) while others (ACKR4) are upregulated in nonagenarians but downregulated in children suffering from HGPS." (PMID 36289702, 2022).